ZFR2 (zinc finger RNA binding protein 2)
Synonyms: KIAA1086
Tractability: PROTAC: its protein half-life has been measured.
Gene: Protein-coding gene on chromosome 19 (3,804,024 to 3,869,038, reverse strand). Ensembl gene ENSG00000105278.
Subcellular location (Human Protein Atlas): Nucleoplasm
Gene Ontology:
Molecular function: double-stranded RNA binding; single-stranded RNA binding; nucleic acid binding; zinc ion binding
Genetic constraint (gnomAD): Loss-of-function variants: 105 observed, 81.48 expected, observed/expected ratio (o/e) 1.29, 90% interval 1.1 to 1.51. The synonymous counts are far from expectation, so gnomAD's model fits this gene poorly and the ratio says little. Missense variants: 1,425 observed, 1,136 expected, observed/expected ratio (o/e) 1.25, 90% interval 1.2 to 1.31. Synonymous variants: 634 observed, 492.44 expected, observed/expected ratio (o/e) 1.29, 90% interval 1.21 to 1.38.
Homologues: Orthologues: chimpanzee ZFR2 (98% identical), macaque ZFR2 (90% identical), pig ZFR2 (68% identical), dog ZFR2 (59% identical), zebrafish zfr2 (53% identical), mouse Zfr2 (51% identical), rat Zfr2 (50% identical), Drosophila melanogaster Zn72D (38% identical), Caenorhabditis elegans zfr-1 (25% identical), Drosophila melanogaster blanks (6% identical), Drosophila melanogaster CG12493 (5% identical), Drosophila melanogaster loqs (5% identical). Paralogues in human: ZFR (49% identical), ILF3 (20% identical), STRBP (19% identical), ADAR (11% identical), ADARB2 (10% identical), ILF2 (10% identical), ADARB1 (8% identical), ADAD1 (6% identical), ADAD2 (6% identical), STAU2 (5% identical), ADAT1 (5% identical), STAU1 (4% identical), and 2 more.
Diseases named in the same sentence as ZFR2 in open-access papers:
ZFR2 is named in the same sentence as 3 diseases in open-access papers, as found by Europe PMC text mining. Sharing a sentence is not in itself a finding about the gene and the disease. The quoted sentences say what the papers report.
tumor (2 papers, 2022 to 2024). "A small number of genes were found significantly differentially expressed in HPV-positive versus HPV-negative tumours (for example NEFH, ZFR2, TAF7L, ZNF541, and TYMS)." (PMID 38643268, 2024). "Screening for circulating tumor DNA from peripheral blood is low invasive and provides fast results, and we suggest screening for HPVP HNSCC using a panel, including RBM24, INHBA, SYCP2, TAFL7, and ZFR2." (PMID 36142875, 2022).
cancer (1 paper, 2017). A tumor composed of atypical neoplastic, often pleomorphic cells that invade other tissues. "Genes characteristic of cancer cells – Oit3, Tnxb, Zfr2, VpreB3, Trim40." (PMID 28031533, 2017).
ZFR2 also shares sentences with these, for which no sentence is quoted: cervical cancer (1 paper).